CD4 (CD4 molecule)
Diseases named in the same sentence as CD4 in open-access papers (continued):
Sharing a sentence is not in itself a finding about the gene and the disease.
tumor (continued). "Previous studies have highlighted that the co-stimulatory molecule CD27 is associated with T cell activation and is up-regulated in tumor-specific CD4 + T cells." (PMID 39033098, 2024). "On the other hand, tumours with a higher infiltration level of PD-L1+ lymphocytes in tumour islets or stroma were significantly associated with higher IL-17A+CD4+ T cell infiltration in tumour islets." (PMID 39409156, 2024). "In the context of the tumor microenvironment (TME), activation of STING pathways in antigen-presenting cells (APCs) enhances the tumor-associated antigen-specific antitumor CD4 and CD8 T cell responses." (PMID 38397152, 2024). "Specifically, CD4+ T lymphocytes engage with tumor-associated macrophages (TAMs) in the tumor microenvironment, promoting M1 polarization and initiating an anti-tumor response." (PMID 38791916, 2024). "For example, predictive biomarkers such as PD-L1 expression, tumor infiltrating lymphocytes (CD8+, CD4+), tumor mutational burden and chemokines (CXCL 9,11,13) can be used to identify EOC patients that do or do not respond to ICI." (PMID 39839766, 2024). "In this model, combinations of ATRA and radiotherapy induce the differentiation of tumor infiltrated monocytes into inflammatory iNOS/TNFα-producing macrophages, contemporaneously enhancing the priming/activation of tumor associated CD8+/CD4+ T-cells." (PMID 38360674, 2024). "Loss of intrahepatic CD4+T lymphocytes accelerated tumor development, implying that NAFLD-induced CD4+T cell loss promotes NAFLD–HCC transition." (PMID 39000005, 2024). "IGSF6 expression was associated with the infiltration of CD8+ T cells and CD4+ T cells in tumors, indicating an active immune response within the tumor microenvironment." (PMID 39108261, 2024). "In contrast, the production of the Th17-associated tumor-promoting cytokines IL-17 and GM-CSF was comparatively lower in both the CD4+ and CD8+ T cells isolated from PMs." (PMID 38384469, 2024). "The persistence of CD8+ T cells is also linked to CD4+ T cell-derived signaling, which helps maintain cytotoxic activity over extended periods, crucial for sustained tumor suppression." (PMID 39769460, 2024). "The upregulation of these chemokines in the tumor-derived CD4+ T cells was very likely associated with the migration toward tumor tissues." (PMID 38343544, 2024). "CCL5 expression by CD4+ tumor-associated lymphocytes in the TME and GC cells causes increased CCL5 release and enhances GC cell line growth." (PMID 39329983, 2024). "On the other hand, higher PD-L1+ lymphocyte infiltration in tumour stroma was associated only with higher Foxp3+CD4+ T cell infiltration in islets and lower M1 macrophage infiltration level in tumour stroma." (PMID 39409156, 2024). "After Hepa1-6 cell injection, Rag1−/− mice reconstituted with Id2fl/flCd4-Cre+ CD8+ T cells along with Id2fl/flCd4-Cre− CD4+ T cells displayed increased tumor susceptibility, as shown by the elevated tumor burden." (PMID 38287103, 2024). "Our previous work showed that bacteria-derived AI-2 was associated with tumour immunity in CRC patients through inducing tumour-associated macrophages and reducing CD4/CD8 ratio in a TNFSF9-dependent manner." (PMID 38725098, 2024). "PRSlow is associated with an activated pyroptosis pathway and greater infiltration of anti-tumor immune cells, including more effector and CD4+ T cells, and with the polarization of tumor-associated macrophages in the tumor center." (PMID 38773976, 2024). "It is known that Tumor-associated neutrophils(TAN) in HCC induce CD4+ T cells to express TGFβ, which promotes Treg cell differentiation and T cell exhaustion, thereby suppressing anti-tumor immune responses." (PMID 39261768, 2024). "In patients with GC, the immune–metabolism signature, which is linked to the ratio of active CD4+ T cells to regulatory T (Treg) cells, can be used to evaluate treatment plans, the tumor microenvironment, and patient prognosis." (PMID 38730659, 2024).
tumor (continued). "Through the utilization of IL-33−/− mice, we demonstrate that the loss of host-derived IL-33 promotes tumor growth and induces alterations in the infiltration patterns of ILC2s, CD4+ T cells, and CD8+ T cells." (PMID 38430390, 2024). "Further, a CD4+ T cell cluster in PBMCs, that co-expressed multiple checkpoint receptors, was negatively associated with CD4+ T cell tumor infiltration." (PMID 38653982, 2024). "The high MMrisk group was positively correlated with B cells, plasma cells, CD4 memory cells, Mast cells, CAFs, monocytes, M2 macrophages, Endothelial, tumor mutation, and most immune checkpoints (PD1, Tim-3, CTLA4, LAG3)." (PMID 38890346, 2024). "To offer further insights into lipid accumulation leading to tumorigenesis, we used a leptin-deficient (obese) mouse model and found that loss of Sirt6 accelerates tumor formation in the liver, accompanlied by reduced CD4+ and CD8+ T cells in the liver." (PMID 38332150, 2024). "This is due to the fact that the variant exerts its pro-tumor effects on IL-23R-bearing immune cells, including tumor-associated macrophages (TAMs), natural killer (NK) cells and CD4+ T-helper cells." (PMID 39796684, 2024). "While dendritic cells and CD4 memory T cells had also found to be associated with anti-tumor immunity in TME and often suggested a better prognosis, which was also consistent with our findings." (PMID 38694875, 2024). "A systematic meta-analysis revealed that total CD4+ T lymphocytes in the tumor stroma compartment were associated with improved overall survival." (PMID 38690280, 2024). "The remaining cells formed the immune and stromal compartments of the tumor, of which the most numerous were cancer-associated fibroblasts, macrophages, CD4+ and CD8+ T-cells, and endothelial cells." (PMID 38499531, 2024). "High-CD1a levels were significantly associated with worse EFS (p = 0.012), and high-CD4 showed numerical differences with better EFS (p = 0.06) in luminal-B tumours." (PMID 38473874, 2024). "For example, an immune-related prognostic seven-gene signature was negatively associated with tumor purity and positively associated with levels of B cell, CD4+ T cell, and CD8+ T cell infiltration." (PMID 38240704, 2024). "The risk scores formed by MPIGs correlate with increased infiltration of tumor-associated fibroblasts, macrophages, CD4+ T cells, and B cells (plasma cells) within UC." (PMID 38696324, 2024). "Previous studies have shown that higher peripheral CD4 + T cells were associated with smaller tumor size." (PMID 38491354, 2024). "A recent study on a small cohort of CCA patients (n = 6) reported that higher levels of CD4+ Treg cells, either in circulation or infiltrating the tumor, were associated with a longer relapse-free survival, though this finding is controversial." (PMID 39408071, 2024). "Although female patients had significantly lower tumor mutational and neoantigen burden than males, pretreatment tumor tissues of female patients had markedly higher CD4, CD4/FOXP3, and CD4/FOXP3/PD‐L1 expression level than male patients." (PMID 38899854, 2024). "This phenotype is accompanied by an altered phenotype of tumor-associated macrophages (TAMs) and a reduction in the percentage of activated effector CD4+ and CD8+ T cells in CRC tumors of DCIR1-deficient mice." (PMID 38532110, 2024). "Immune cells like Th1 cells, Th2 cells, Tregs, myeloid derived suppressor cells, tumor associated macrophages, DCs, NKs, CD4+ and CD8+ T cells are all involved in the regulation of immune response in the tumor microenvironment." (PMID 38571964, 2024). "In line with this, neoHELP variants containing wild-type counterparts of the CD4+ or CD8+ T cell neoantigens displayed reduced tumor control." (PMID 39040850, 2024). "Adding to the role of IL-17 as a tumor-promoting cytokine, Salazar Y. and colleagues demonstrated in humans that a high frequency of Th9 or Th17 among CD4+ T lymphocytes was significantly associated with decreased survival in NSCLC patients." (PMID 38690280, 2024).
tumor (continued). "Multifunctional MGC hydrogel loaded with DNA/DOX complex was directly implanted into the surgical site after tumor resection to locally activate tumor-associated immune cells (e.g., cytotoxic T cells, CD4+ cells, and regulatory T cells)." (PMID 38532906, 2024). "Th17 T helper cells are derived from naive CD4+ T cells and are implicated in the tumor immunological milieu." (PMID 38672732, 2024). "In another cohort analysis, although CD4+ infiltration into NSCLC was associated with advanced tumor stages and lymph node spread, high CD8+ frequency in TILs was related to improvement in overall survival." (PMID 38690280, 2024). "So, we can secondly conclude that potential benefits associated with the presence of tumor-specific TCR-armed CTX CD4+ are now preclinically demonstrated." (PMID 38545119, 2024). "In contrast, a Zn-deficient diet enhanced the frequency of tumor-infiltrated IFN-γ+ TNF-α+ CD4+ T cells, while the intake of high Zn reduced the frequency of these cells." (PMID 39247196, 2024). "Among CD4+ T-cell populations, Tregs were the predominant subset and highly enriched in the tumor microenvironment of HBV-associated HCC, with the highest accessibility at the forkhead box P3 (FOXP3) loci." (PMID 38793588, 2024). "During our investigation, we observed increased expression levels of crucial anti-tumor immune cell populations, such as NK cells, CD4 + T lymphocytes, and macrophages, in the high-risk group." (PMID 38342890, 2024). "For example, possible differentiation derived from single‐positive T‐cell tumour‐associated CD4/CD8 double‐positive T (DPT) cells recently identified at the tumour border exhibit synergistic expression of PD‐1, HLA‐DR, ICOS, and CD45RO." (PMID 39350478, 2024). "The favorable prognostic effect of Tregs in CRC has been implied in several studies, while others have reported that Tregs promote CRC progression by suppressing the CD4+T-cell response to tumor-associated antigens." (PMID 38951801, 2024). "Spatial-immunophenotyping provided evidence that tumor-cell AXL-upregulation and adverse mutations modulate the tumor microenvironment in favor of infiltrating, activated neutrophils over anti-tumor immune-subsets including CD4 and CD8 T-cells." (PMID 39238637, 2024). "CCAs demonstrate diverse TILs, with a high density of CD4+ T cells at the tumor margin being associated with improved disease-free survival (DFS) and OS." (PMID 39845973, 2024). "An animal study examined the effect of Il-12 administration with MRgFUS causing BBBD; the results showed that an increased ratio of lymphocytes T CD8 to CD4 in the tumor region caused retarded tumor progression and an improvement in the average survival rate." (PMID 39766134, 2024). "Co-injection of MC38 and EGCs resulted in increased tumor growth associated with higher numbers of TAMs, as well as CD4+ T cells, CD8+ T cells, and Treg cells compared to mice orthotopically injected with MC38 cells alone." (PMID 39030280, 2024). "Specifically, patients who exhibited a CD4 count lower than 200 IU/mm3 after a 3-month follow-up period were more susceptible to tumor recurrence." (PMID 39957858, 2024). "Mn2+-deficient mice exhibited higher tumor burden and fewer tumor-infiltrating CD4+/CD8+ T cells than those in normal mice." (PMID 38175694, 2024). "The present study further revealed that ADAM10 was negatively associated with T cells CD4, T cells CD4 naive, macrophages, MHCs, AZs, monocytes, and other immune cells associated with tumor infiltration." (PMID 39211038, 2024). "Although CD8+ T cells remain the primary focus of therapeutic target research, CD4+ T cells are increasingly being studied for their role in tumor immunity, However, the mechanisms underlying their activation are not yet fully understood." (PMID 39181686, 2024).
tumor (continued). "RT causes the release of tumor antigens, which leads to increased tumor antigen presentation, thereby recruiting and activating antitumor subsets, such as CD4+ and CD8+ T cells, cytotoxic NK cells, and CD8+ CD56+ natural killer T (NKT) cells." (PMID 38974233, 2024). "We showed that the congenital deficiency of CD11chi DCs enhanced the proportion of tumor-infiltrating CD4+ TEM cells, while it reduced their expressions of certain immune checkpoint molecules." (PMID 39206204, 2024). "Studies have indicated that Batf1-dependent IL-23R+IL-6+CD4+ Th17 cells are crucial for regulating IL-23-driven colitis-associated tumor formation and the progression of sporadic colon tumors." (PMID 39796684, 2024). "In a mouse model, elevated cancer cell glycolytic activity in the TME was linked to the impaired function of anti-tumor CD4+ T-cells, resulting in reduced glucose uptake and effector T-cell function." (PMID 39227970, 2024). "Key players within the TME include tumor-associated macrophages (TAMs), CD4+ T (helper T) cells, dendritic cells (DCs), regulatory T cells (Tregs), and tumor-associated neutrophils (TANs), each playing a vital role in CRC’s metastatic journey." (PMID 38415252, 2024). "Paradoxically, the presence of neutrophils is associated with poor prognosis and tumor infiltration with CD4+ T cells has been linked to tumor progression and metastasis." (PMID 38711620, 2024). "This leads to the conversion of tumor-associated CD4+ T cells to the Th1 type, which enhances the immune response." (PMID 39482784, 2024). "Only PD-L1 IC and CPS > 10% was associated with higher Foxp3+CD4+ T cells infiltration level in tumour tissue." (PMID 38541208, 2024). "We further confirmed the genetic changes in tumor-associated CD4+ T cells of effector memory T cells and regulatory T cells in the TME after Ce6-mediated PDT treatment." (PMID 37762216, 2023). "Infiltration of neoantigen-specific Th1 CD4+ T cells within the tumor was associated with a significant reduction in FOXP3+ Tregs." (PMID 38063199, 2023). "Compared with low-risk groups, infiltration of tumor immune cells, including memory B, activated mast, resting mast, plasma, and activated memory CD4 + T cells in high-risk groups was significantly different." (PMID 36814224, 2023). "These immune components included tumor-associated macrophages (TAMs), natural killer (NK) cells, CD4+ T cells, CD8+ T cells, B cells, macrophages, mast cells, dendritic cells, among others." (PMID 38042769, 2023). "Combined treatment resulted in significant tumor growth suppression and survival extension compared with either therapy alone or control, and was associated with an increase in tumor-infiltrating CD4+ and CD8+ T cells." (PMID 36678880, 2023). "Another probable explanation is that the CB2-deficient DCs shift naïve CD4+ T cells towards a Th2 subtype, thus preventing tumor cell apoptosis." (PMID 37175480, 2023). "In PDAC, ES-TLS+ tumors are enriched with IgG1-like transformed memory B cells and memory CD4+ T cells with persistent immune memory function and reduced tumor mutational burden (TMB)." (PMID 37529035, 2023). "Tumor immune infiltration cell analysis showed that the low-risk group had higher levels of resting CD4 memory T cells and lower levels of M0 macrophages." (PMID 37072786, 2023). "In sunitinib-treated patients, a higher percentage of tumor-infiltrating CD4+ T lymphocytes was associated with shorter OS and PFS." (PMID 37842234, 2023). "This relationship has also been investigated in OPSCC, with a higher infiltration of the tumor with CD4+ and CD8+ T cells associated with a better OS, DSS as well as a lower T stage." (PMID 36680237, 2023). "Although the predisposition of Th2 CD4+ T cells in tumor have been implicated in BCG failure, the precise contribution of intratumoral CD8+ T cells in influencing the therapeutic efficacy of BCG remains largely elusive." (PMID 37566017, 2023).
tumor (continued). "In the high-risk group, there were more infiltrating B cell plasma, T cell follicular helper, T cell regulatory (Tregs), macrophage M0, neutrophils, and T cell CD4+ memory activated within tumor tissues than in the low-risk group." (PMID 37854038, 2023). "Treg cells are a subset of CD4+ T cells which play a key role in tumor-associated immunosuppression." (PMID 36845095, 2023). "This suppression of tumour is associated with an increased production of T cells such as CD4 + and CD8 + cells as well as an increased apoptosis of cancer cells." (PMID 37041200, 2023). "Within the TME of BCC lesions, the most prevalent cellular players include cancer-associated fibroblasts, tumor-associated macrophages, CD4+ and CD8+ T cells, regulatory T cells, and dendritic cells, as well as their differentiated subset Langerhans cells." (PMID 37173918, 2023). "In breast cancer patients, dormant tumor cells in the bone marrow are closely associated with increased presence of CD4+ and CD8+ T cells." (PMID 37440925, 2023). "FOXP3 in tumor-infiltrating CD4+ T cells is generally associated with an intrinsic capacity to suppress tumor immunity." (PMID 37868998, 2023). "The activation of CD4+ T cells leads to a significant increase in their proliferation as well as the activation of tumor-associated macrophages, resulting in an increased CD4+/CD8+ ratio and enhanced tumor immunity." (PMID 37762285, 2023). "Of note, another study of human CRC specimens illustrated that those with high densities of CD4+T were associated with a lower likelihood of tumour relapse and improved OS, which are consistent with the findings from our study." (PMID 36936424, 2023). "In tumor infiltrating immune cells, the risk score was negatively correlated with tumor-infiltration lymphocytes (TILs) (including CD4 + T cells, NK, and CD8 + T cells), which played an important role in immunotherapy." (PMID 37596527, 2023). "Selenium-containing polysaccharides from the roots of astragalus membranaceus reduced CD4+ T cell apoptosis and serum cytokine dysregulation caused by tumor transplantation, which promoted the cytotoxic activities of NK cells and CD8+ T cells." (PMID 37741920, 2023). "ccRCC tumors are characterized by rich leukocyte infiltrates and an abundance of intratumoral CD8+ and CD4+ T cells, which are associated with high tumor grade and shorter patient survival." (PMID 37190141, 2023). "Higher baseline CD4+ T cells, dendritic cells, and macrophages were associated with worse OS in less than 10-μm distance to tumor cells, but related with better OS in the farther distance." (PMID 37275884, 2023). "AIRE‐related tumour‐associated antigen‐reactive clone depletions of both CD4+ and CD8+ T cells can culminate in suppressed immune responses." (PMID 37403792, 2023). "Nevertheless, several studies have reported CXCL13-producing CD4+ T cells, which have been associated with favorable outcomes of tumor immunity." (PMID 38077321, 2023). "Lastly, 39% of analysed GBM patient samples showed PD-L1+ staining of tumour cells that was associated with elevated levels of CD4+ and CD8+ lymphocytes." (PMID 37370741, 2023). "CD4+ cells were significantly associated with survival in the tumor region, total region, and Top3 density (DFS, P=0.0213; OS, P=0.0728)." (PMID 37090736, 2023). "Recent evidence also has indicated that the presence of activated CD4 T cells in tumor tissue is associated with a better prognosis." (PMID 37976136, 2023). "In contrast to cDC1s, cDC2s present tumor-associated antigens directly to CD4+ T cells or transfer them to lymphoid tissue-resident DCs." (PMID 37183207, 2023). "Higher levels of dendritic cells, T helper cells, CD4+ T cells, and tumor-infiltrating lymphocytes were also observed in the low-risk group." (PMID 37940859, 2023). "IFNG, AC006369.1, and CCR7 were closely linked with the tumor microenvironment components (e.g., macrophages, CD4/CD8 T cells, NK cells), and immune checkpoints (notably PD1/PD-L1)." (PMID 37408777, 2023).